SLC38A7 (solute carrier family 38 member 7)
Description:
Symporter that selectively cotransports sodium ions and amino acids, such as L-glutamine and L-asparagine from the lysosome into the cytoplasm and may participates in mTORC1 activation. The transport activity requires an acidic lysosomal lumen.
Synonyms: SNAT7; FLJ10815
Tractability: Antibody: UniProt predicts a signal peptide or a membrane-spanning region; the Human Protein Atlas places it where antibodies can reach. PROTAC: ubiquitination databases record sites on it; its protein half-life has been measured.
Gene: Protein-coding gene on chromosome 16 (58,663,015 to 58,684,770, reverse strand). Ensembl gene ENSG00000103042.
Subcellular location: Lysosome membrane; Cell projection, axon
Subcellular location (Human Protein Atlas): Cytosol; Plasma membrane; Nucleoplasm
Gene Ontology:
Molecular function: L-asparagine:sodium symporter activity; L-glutamine:sodium symporter activity; protein binding; L-asparagine transmembrane transporter activity; L-glutamine transmembrane transporter activity
Biological process: asparagine transport; glutamine transport; amino acid transmembrane transport; sodium ion transport
Cellular component: lysosomal membrane; axon; neuronal cell body
Genetic constraint (gnomAD): Loss-of-function variants: 29 observed, 48.63 expected, observed/expected ratio (o/e) 0.6, 90% interval 0.44 to 0.81. The upper end of that interval is the gene's LOEUF score, 0.81, which puts it in group 3 of 6, group 1 being the genes least tolerant of losing a copy. Missense variants: 483 observed, 601.01 expected, observed/expected ratio (o/e) 0.8, 90% interval 0.75 to 0.87. Synonymous variants: 244 observed, 239.7 expected, observed/expected ratio (o/e) 1.02, 90% interval 0.92 to 1.13.
Homologues: Orthologues: chimpanzee SLC38A7 (99% identical), macaque SLC38A7 (98% identical), mouse Slc38a7 (95% identical), rabbit SLC38A7 (94% identical), rat Slc38a7 (94% identical), dog SLC38A7 (94% identical), pig SLC38A7 (94% identical), guinea pig SLC38A7 (94% identical), zebrafish slc38a7 (70% identical), tropical clawed frog slc38a7 (68% identical), Drosophila melanogaster CG32079 (16% identical), Caenorhabditis elegans Y18D10A.23 (16% identical), and 15 more. Paralogues in human: SLC38A8 (38% identical), SLC38A1 (23% identical), SLC38A2 (23% identical), SLC38A4 (23% identical), SLC38A6 (23% identical), SLC38A3 (21% identical), SLC38A5 (20% identical), SLC38A11 (19% identical), SLC32A1 (18% identical), SLC36A2 (18% identical), SLC38A9 (18% identical), SLC36A1 (17% identical), and 3 more.
Diseases named in the same sentence as SLC38A7 in open-access papers:
SLC38A7 is named in the same sentence as 90 diseases in open-access papers, as found by Europe PMC text mining. Sharing a sentence is not in itself a finding about the gene and the disease. The quoted sentences say what the papers report.
Insulin resistance (2 papers, 2014 to 2025). Increased resistance towards insulin, that is, diminished effectiveness of insulin in reducing blood glucose levels. "The SLC38A7 gene, encoding a Na+-coupled glutamine transporter, is linked to the mTORC1 signaling pathway, which is crucial in nutrient sensing and insulin resistance." (PMID 40141237, 2025).
diabetic retinopathy (1 paper, 2022). "Stratification of patients based on presence/absence of vascular complications highlighted significant associations of SLC7A8-rs3783436 and SLC38A7-rs9806843 with diabetic retinopathy." (PMID 36364703, 2022).
gastric cancer (1 paper, 2024). A primary or metastatic malignant neoplasm involving the stomach. "SLC38A7 mRNA and protein levels in human gastric cancer cell lines (AGS, HGC27, MKN45, and NCIN87) were higher than those in normal human gastric epithelium cells (GES-1), with the highest expression detected in AGS cells and the lowest expression detected in HGC27 cells." (PMID 39357829, 2024).
hepatocellular carcinoma (1 paper, 2023). A malignant tumor that arises from hepatocytes. "created a novel Hepatocellular Carcinoma prediction model that integrates 7 GlnMgs, including SLC1A5, GAPDH, SLC38A1, SLC38A7, FTCD, MTHFS, and GOT2 might be utilized to predict prognosis in HCC." (PMID 37377916, 2023).
lung squamous cell carcinoma (1 paper, 2024). "High SLC38A7 expression was associated with shorter survival of GC patients, which is consistent with a previous study on lung squamous cell carcinoma." (PMID 39357829, 2024). "High SLC38A7 expression predicts poor prognosis and is a potential therapeutic target in lung squamous cell carcinoma." (PMID 39357829, 2024). "In addition to the role of SLC38A7 in transporting glutamine, it has recently been identified as a poor prognostic marker in small-cell lung cancer and lung squamous cell carcinoma and regulates cell proliferation." (PMID 39357829, 2024).
cancer (82 papers, 2013 to 2025). A tumor composed of atypical neoplastic, often pleomorphic cells that invade other tissues. "SLC38A7 silencing suppressed cell viability, migration, invasion, oxidative phosphorylation, and mitochondrial function in cancer cells." (PMID 39357829, 2024). "Several SLC38 isoforms have previously been linked to cell proliferation, invasion, migration and/or angiogenesis, including SLC38A2, SLC38A3, SLC38A6 and SLC38A7, supporting their involvement in cancer progression." (PMID 38254895, 2024). "On the other hand, the sodium- dependent amino acid transporter SLC38A7, which was shown to be essential for the extracellular protein–dependent growth of cancer cells, was the most stable with a dynamic range of protein expression of ∼2-fold." (PMID 36791992, 2023). "The SLC38A7 transporter has been proposed as a new target for glutamine-related anti-cancer drugs, as it is required for cancer cell growth." (PMID 35326372, 2022). "In a previous study, SLC38A7 co-localized with lysosomes in HeLa cells and was found to mediate flux of glutamine and asparagine and hence crucial for growth of cancer cells." (PMID 29868606, 2018). "Furthermore, another study has suggested that SLC38A7 is the main lysosomal glutamine/asparagine exporter required for extracellular protein-dependent growth of cancer cells." (PMID 33375025, 2020). "SLC6A14 (ATB0,+) that broadly accepts large neutral amino acids, as well as SLC38A2 (SNAT2), SLC38A3 (SNAT3) and SLC38A7 (SNAT7) that accept some large neutral amino acids such as His, Met and Leu are known to be upregulated in certain types of cancers." (PMID 36071551, 2022).
tumor (65 papers, 2006 to 2025). "SLC38A7 expression also showed a significant association with tumor size (p = 0.028) and TNM stage (p = 0.027)." (PMID 39357829, 2024). "SLC38A6 and SLC38A7 expressions in tumor tissue sections were higher than those in normal tissue sections." (PMID 39357829, 2024). "In the present study, analysis of TCGA data and tumor tissue microarrays revealed upregulation of SLC38A7 in GC." (PMID 39357829, 2024). "Our findings may provide insights into the biological activities of SLC38A7 in carcinogenesis and tumor progression." (PMID 39357829, 2024). "By analyzing TCGA data in the GEPIA database, we found that the expression levels of multiple SLC38A family members (including SLC38A2, SLC38A4, SLC38A5, SLC38A6, SLC38A7, SLC38A8, SLC38A9, and SLC38A10) were significantly upregulated in GC tumor tissues." (PMID 36918802, 2023).
retinopathy (1 paper, 2022). "This proposed role of SLC38A7 provides a possible mechanism on which to base the association between the rs9806843 variant of this gene and retinopathy we found." (PMID 36364703, 2022). "A protective effect against retinopathy was also observed for the intronic SNP rs9806843 in SLC38A7 gene which encodes a sodium-coupled AAT, known also as SNAT7, which has glutamine as the preferred substrate." (PMID 36364703, 2022).
SLC38A7 also shares sentences with these, for which no sentence is quoted: breast carcinoma (21 papers); infection (10); colorectal cancer (9); glioma (8); pancreatic cancer (8); brain tumor (5); intrauterine growth restriction (5); cystinuria (4); diabetes (4); melanoma (3); prostate carcinoma (3); thyroid cancer (3); autism spectrum disorder (2); inflammation (2); lung carcinoma (2); lung disease (2); lymphoma (2); metabolic disease (2); metastatic disease (2); non-small cell lung carcinoma (2); osteosarcoma (2); triple-negative breast carcinoma (2); Adrenal Gland (1); adrenal gland neoplasm (1); age-related hearing-loss (1); Alzheimer disease (1); bacterial infection (1); biliary tract cancer (1); bipolar disorder (1); bladder cancer (1).
A further 52 diseases each share a sentence with SLC38A7 in 1 paper.